LRIG2 (leucine rich repeats and immunoglobulin like domains 2)
Synonyms: LIG-2; KIAA0806; LIG2; UFS2
Tractability: Antibody: UniProt places it where antibodies can reach, with high confidence; UniProt predicts a signal peptide or a membrane-spanning region; its Gene Ontology location is reachable by antibodies, with medium confidence. PROTAC: ubiquitination databases record sites on it.
Gene: Protein-coding gene on chromosome 1 (113,073,179 to 113,132,260, forward strand). Ensembl gene ENSG00000198799.
Subcellular location: Cell membrane; Cytoplasm
Subcellular location (Human Protein Atlas): Golgi apparatus; Nucleoplasm
Gene Ontology:
Molecular function: protein binding; signaling receptor activity; signaling receptor binding
Biological process: sensory perception of sound
Cellular component: plasma membrane; cytoplasm; growth cone; intracellular vesicle; membrane
Genetic constraint (gnomAD): Loss-of-function variants: 70 observed, 89.88 expected, observed/expected ratio (o/e) 0.78, 90% interval 0.64 to 0.95. The upper end of that interval is the gene's LOEUF score, 0.95, which puts it in group 4 of 6, group 1 being the genes least tolerant of losing a copy. Missense variants: 1,076 observed, 1,221 expected, observed/expected ratio (o/e) 0.88, 90% interval 0.84 to 0.93. Synonymous variants: 432 observed, 453.71 expected, observed/expected ratio (o/e) 0.95, 90% interval 0.88 to 1.03.
Homologues: Orthologues: macaque LRIG2 (98% identical), pig LRIG2 (93% identical), guinea pig LRIG2 (92% identical), rabbit LRIG2 (91% identical), rat Lrig2 (90% identical), mouse Lrig2 (89% identical), chimpanzee LRIG2 (88% identical), tropical clawed frog lrig2 (69% identical), dog LRIG2 (60% identical), zebrafish lrig2 (58% identical), Caenorhabditis elegans sma-10 (23% identical), Drosophila melanogaster kek3 (15% identical), and 2 more. Paralogues in human: LRIG3 (55% identical), LRIG1 (48% identical), LGR6 (19% identical), LGR5 (18% identical), LGR4 (17% identical), TRIL (15% identical), CPN2 (13% identical), CHADL (12% identical), LRIT3 (12% identical), ELFN2 (12% identical), LRIT1 (12% identical), LRRC24 (12% identical), and 10 more.
Diseases named in the same sentence as LRIG2 in open-access papers:
LRIG2 is named in the same sentence as 50 diseases in open-access papers, as found by Europe PMC text mining. Sharing a sentence is not in itself a finding about the gene and the disease. The quoted sentences say what the papers report.
glioma (12 papers, 2013 to 2025). A benign or malignant brain and spinal cord tumor that arises from glial cells (astrocytes, oligodendrocytes, ependymal cells). "LRIG2, which is the only one described as a tumor promoter, has been associated with higher grades of gliomas and poor survival in patients with oligodendroglioma." (PMID 41201961, 2025). "LRIG2-deficient mice developed PDGFB-induced gliomas less frequently compared to control mice and if they did, the tumors were of lower malignancy." (PMID 41201961, 2025). "In contrast to LRIG1, the less studied LRIG2 is believed to be a tumor promoter that enhances the development of glioma and is associated with higher grades." (PMID 41201961, 2025). "Here, we addressed the functions of LRIG2 and LRIG2 ectodomain in the proliferation and apoptosis of glioma and the possible underlying mechanisms." (PMID 25353163, 2014). "LRIG2 is permissive for oligodendroglial and glioblastoma-like brain tumour formation in a mouse model and downregulation of LRIG2 in cultured glioma cells led to ligand-mediated loss of the epidermal growth factor receptor (an RTK), cell cycle arrest and increased apoptosis." (PMID 24691552, 2014). "Recently, it was found that Lrig2-deficient mice were protected against PDGFB-induced glioma." (PMID 25353163, 2014). "On mRNA level, the same was seen for LRIG2, were low grade glioma expressed significantly more LRIG2 than high grade glioma." (PMID 41201961, 2025). "The expression negatively correlated with WHO tumor grade, both LRIG1 and LRIG2 were decreased in high grade glioma." (PMID 41201961, 2025). "In this study, in contrast to previous findings, LRIG2 mRNA levels were significantly higher in low compared to high-grade glioma." (PMID 41201961, 2025). "In this study, our findings reveal the anti-angiogenic role of LRIG3 and affirm that LRIG3 has a functionally antagonistic relationship with LRIG2 in glioma angiogenesis." (PMID 33718179, 2021). "Little is known about LRIG2, although it has been shown to be permissive for glial tumour growth in vivo, and in a glioma cell culture model, LRIG2 interacts with epidermal growth factor receptor and modulates intracellular signalling." (PMID 26315301, 2016). "There was a significant difference in LRIG2 IR between low-grade gliomas and high-grade gliomas (P = 0.004), which indicated that the expression level of LRIG2 protein in HGGs was much higher compared to that in LGGs." (PMID 25353163, 2014). "We firstly investigated the relationship between the expression level of LRIG2 and the grade of glioma." (PMID 25353163, 2014). "Taken together, we report for the first time that LRIG2 expression levels positively correlate with the grade of glioma." (PMID 25353163, 2014). "To further confirm the results, we collected the fresh human glioma samples of different grade to investigate the expression levels of LRIG2 proteins by immunnohistochemical staining." (PMID 25353163, 2014). "To investigate the expression levels of LRIG2 in different grade of glioma, we firstly used public TCGA data repositories as our primary source of samples." (PMID 25353163, 2014). "In any case, the results herein presented, showing that Lrig2 promoted PDGFB-induced glioma in mice, are consistent with the previous finding that LRIG2 expression predicts poor survival in human oligodendroglioma patients." (PMID 24023893, 2013). "The phenotype of Lrig2E12-/- mice showed that Lrig2 was a promoter of PDGFB-induced glioma, and Lrig2 appeared to have important molecular and developmental functions that were distinct from those of Lrig1 and Lrig3." (PMID 24023893, 2013). "LRIG3 was, in contrast to LRIG1 and LRIG2, significantly increased in glioma compared to control tissue (1.354 ± 0.89 vs. 0.746 ± 0.242, p = 0.039), with highest difference to grade II glioma (1.556 ± 0.702 vs. 0.746 ± 0.242, p = 0.0.0002)." (PMID 41201961, 2025).
glioma (continued). "The study found that the downregulation of LRIG2 expression decreased the proliferation rate, which resulted in G0/G1 arrest and the increased spontaneous apoptosis, cell adhesion and invasion capability of the glioma cell line." (PMID 25013483, 2014). "Firstly, we found that LRIG2 expression levels positively correlated with the grade of glioma." (PMID 25353163, 2014). "However, our data on LRIG2 indicate that its role in glioma may be more complex than previously thought, warranting further investigation." (PMID 41201961, 2025). "Moreover, LRIG2 exerted a proangiogenic effect by stimulating VEGF production in glioma." (PMID 36183058, 2022). "Because the gliomas in our animal model were induced by PDGFB, we find it likely that the tumor promoting effect of Lrig2 was mediated by regulation of PDGF signaling." (PMID 24023893, 2013). "LRIG2 was proven as miR-503 target by luciferase assay, knockdown of LRIG2 reduced VEGFA expression level along with the condition of miR-503 inhibitor, therefore, miR-503 regulated angiogenesis in glioma by reducing LRIG2 expression followed by downregulation of VEGFA expression." (PMID 33762949, 2021). "LRIG2 belongs to the leucine-rich repeats and immunoglobulin-like domains family and regulates epidermal growth factor receptor (EGFR) signaling pathway, and downregulation of LRIG2 suppressed angiogenesis in glioma." (PMID 33762949, 2021). "This might suggest post-transcriptional modifications of LRIG2 protein expression in gliomas, such like regulation via miRNA or a negative feedback loop, which then results in opposing mRNA and protein levels." (PMID 41201961, 2025). "It has been reported that LINC00461/miRNA-149-5p/LRIG2 existed in hepatocellular carcinoma, LINC00461/miRNA-15a/miRNA-16/Bcl-2 happened in multiple myeloma, LINC00461/miRNA-30a-5p/integrin β3 occurred in breast cancer, and LINC00461/miRNA-411-5p/TOP2A participated in glioma." (PMID 33817241, 2020).
glioblastoma (8 papers, 2013 to 2023). The most malignant astrocytic tumor (WHO grade IV). "In this study, we studied the functions of the full-length LRIG2 and LRIG2 ectodomain in the progression of glioblastoma to gain insight into the mechanism underlying the role of LRIG2." (PMID 25353163, 2014). "Further, in order to provide more compelling evidence to support our proposal, we explored the possible mechanisms underlying the effects of full-length LRIG2 and LRIG2 ectodomain on the proliferation and apoptosis of glioblastoma." (PMID 25353163, 2014). "To further confirm the role of LRIG2 in glioblastoma and explore the possible underlying mechanisms, we established glioblastoma cells with stable expressions of the full-length LRIG2." (PMID 25353163, 2014). "To explore the possible mechanisms underlying the forementioned effects of full-length LRIG2 and LRIG2 ectodomain on the glioblastomas, we examined whether LRIG2 or LRIG2ecto could interact with EGFR." (PMID 25353163, 2014). "Elevated LRIG2 (Leucine Rich Repeats And Immunoglobulin Like Domains 2) gene expression in glioblastoma cells triggers CD47 upregulation and activates the CD47-SIRPα anti-phagocytic axis." (PMID 37700840, 2023). "LRIG2 promotes proliferation and inhibits apoptosis of glioblastoma cells through activation of EGFR and PI3K/Akt pathway." (PMID 32488114, 2020). "Ubiquitous LRIG2 knockout mice were protected against glioblastoma, demonstrating that LRIG2 plays a crucial role in glioblastoma initiation and progression." (PMID 31580518, 2019). "Overexpression of LRIG2 ectodomain promoted the proliferation and inhibited the apoptosis of glioblastoma cells in vitro and in vivo in a similar manner to the full-length LRIG2." (PMID 25353163, 2014). "Previously, we demonstrated that downregulation of LRIG2 expression by RNA interference increased spontaneous apoptosis of glioblastoma cells in vitro." (PMID 25353163, 2014). "LRIG2 ectodomain, with potent pro-tumor effects, holds promise for providing a new therapeutic target for the treatment of glioblastoma." (PMID 25353163, 2014). "Taken together, glioblastoma cell lines stably expressing full-length LRIG2 and LRIG2 ectodomain were successfully established." (PMID 25353163, 2014). "Collectively, we demonstrated that full-length LRIG2 and LRIG2 ectodomain overexpressions inhibited the spontaneous apoptosis of glioblastoma cells through mitochondrial pathway by stabilizing the mitochondria membrane potential." (PMID 25353163, 2014). "Further, we demonstrated for the first time that soluble LRIG2 ectodomain was capable of being released from glioblastoma cells and exerted a pro-proliferative effect." (PMID 25353163, 2014). "Taken together, these results revealed that full-length LRIG2 as well as LRIG2 ectodomain promoted the growth of glioblastoma cells in vitro." (PMID 25353163, 2014). "Strikingly, the anti-Flag-reactive soluble protein was detected in the cell culture supernatants of cells with full-length LRIG2 overexpression, suggesting that the flag tagged protein fragment was released from the surface of glioblastoma cells." (PMID 25353163, 2014). "Most strikingly, we demonstrate for the first time that the soluble LRIG2 ectodomain is capable of being released from glioblastoma cells." (PMID 25353163, 2014). "Further, we evaluated the effects of the soluble LRIG2 ectodomain in the conditioned medium on the proliferation of glioblastoma cells." (PMID 25353163, 2014). "Noteworthy, we previously demonstrate that downregulation of LRIG2 inhibits glioblastoma cell growth in vitro." (PMID 25353163, 2014). "In line with the forementioned results, we showed that overexpression of full-length LRIG2 promoted the proliferation and inhibited the apoptosis of glioblastoma cells in vitro and in vivo." (PMID 25353163, 2014). "Strikingly, we demonstrated for the first time that the soluble LRIG2 ectodomain was capable of being secreted by glioblastoma cells and exerted a pro-proliferative effect." (PMID 25353163, 2014).
glioblastoma (continued). "Both full-length LRIG2 and LRIG2 ectodomain promoted the proliferation and inhibited the apoptosis of glioblastoma in vitro and in vivo probably through enhancing the EGFR activation and its downstream PI3K/Akt pathway." (PMID 25353163, 2014). "Firstly, we demonstrated that both LRIG2 and LRIG2ecto overexpressions markedly promoted the growth of U87 and U251 glioblastoma cells." (PMID 25353163, 2014). "All injected Lrig2E12+/+ mice developed Lrig2 expressing oligodendroglial brain tumors of lower grade (82%) or glioblastoma-like tumors of higher grade (18%)." (PMID 24023893, 2013). "Going forward, it will be important to determine how LRIG2 ectodomain is released from glioblastoma cells, whether this kind of release is universal, and how LRIG2 ectodomain interact with EGFR and enhance the activation of EGFR." (PMID 25353163, 2014). "Therefore the mechanisms underlying the function differences between LRIG2 ectodomain and LRIG1 ectodomain in the progression of glioblastoma are needed to be further addressed in the future." (PMID 25353163, 2014). "We believe that LRIG2 ectodomain may provide a promising therapeutic target in the treatment of glioblastoma multiform in the future." (PMID 25353163, 2014). "Collectively, we demonstrated for the first time that the soluble LRIG2 ectodomain could be released from the glioblastoma cells and promote the proliferation of glioblastoma cells in vitro." (PMID 25353163, 2014). "Further, we investigated whether LRIG2 or LRIG2ecto altered glioblastoma anchorage-independent growth, a property that mimics tumorigenesis in vivo." (PMID 25353163, 2014). "Most strikingly, we for the first time demonstrated that overexpression of LRIG2 ectodomain could also significantly decrease the spontaneous apoptotic rates of U87 and U251 glioblastoma cells." (PMID 25353163, 2014). "We next determined whether the effects exerted by LRIG2 and LRIG2ecto overexpressions on the growth and apoptosis of glioblastoma cells in vitro could be demonstrated in vivo." (PMID 25353163, 2014). "Consequently, we for the first time demonstrated that the soluble LRIG2 ectodomain was capable of being secreted by glioblastoma cells." (PMID 25353163, 2014). "Combined with our previous reported finding that downregulation of LRIG2 inhibits glioblastoma cell growth in vitro, our results provided compelling evidences in support of the proposal that full-length LRIG2 served as a tumor promoter in glioblastoma." (PMID 25353163, 2014). "As previous study demonstrated that soluble LRIG1 ectodomains could be released from the full-length LRIG1, we wanted to address whether soluble LRIG2 ectodomains could be released from glioblastoma cells." (PMID 25353163, 2014). "Both full-length LRIG2 and LRIG2 ectodomain potently promote the proliferation and inhibited the apoptosis of glioblastoma cells in vitro and in vivo through physically interacting with EGFR, stabilizing EGFR, and enhancing EGFR activation and its downstream PI3 K/Akt pathway." (PMID 25353163, 2014). "Increased LRIG2 expression correlates with a poorer prognosis in patients with oligodendroglioma, cervical SCC, non‐small cell lung cancer, and glioblastoma." (PMID 31580518, 2019). "The results revealed that the ratios of JC-1 FL-2/FL-1 of glioblastoma cells transduced with LRIG2 or LRIG2ecto were robustly increased compared to the corresponding control cells, which indicated that LRIG2 and LRIG2ecto overexpressions both stabilized the MMP of glioblastoma cells." (PMID 25353163, 2014). "However the effect of overexpression of full-length LRIG2 or LRIG2 ectodomain on the growth of glioblastoma cells has not been addressed yet." (PMID 25353163, 2014).
urofacial syndrome (7 papers, 2013 to 2022). "Mutations in leucine-rich-repeats and immunoglobulin-like-domains 2 (LRIG2) or in heparanase 2 (HPSE2) cause urofacial syndrome, a devastating autosomal recessive disease of functional bladder outlet obstruction." (PMID 30885509, 2019). "Mice with homozygous targeted Lrig2 mutations had urinary defects resembling those found in urofacial syndrome." (PMID 30885509, 2019). "In an individual with biallelic variants in LRIG2, the causal gene for urofacial syndrome (MIM 615112), and a homozygous LIG4 missense variant, the affected child had recurrent episodes of urosepsis, secondary to severe vesicoureteral reflux, leading to left kidney hypoplasia and scarring." (PMID 32534991, 2020). "Interestingly, it has been reported that mutations in Lrig2 cause urofacial syndrome (UFS), an autosomal-recessive disease characterized by congenital urinary bladder dysfunction associated with a significant risk of kidney failure and abnormal facial expression." (PMID 27555809, 2016). "Several monogenic causes of other congenital bladder outflow obstruction disorders have been described including BNC2 in urethral stenosis; FLNA in syndromic urethral anomalies; HPSE2 and LRIG2 in urofacial syndrome; CHRM3 in prune-belly like syndrome; and MYOCD in megabladder." (PMID 36124557, 2022). "Although Lrig2 phenotypes have not yet been described in mice, loss of LRIG2 causes Urofacial Syndrome in humans, which is characterized by abnormal bladder function and altered facial expression, possibly due to abnormal innervation." (PMID 24086156, 2013).
melanoma (6 papers, 2019 to 2024). A malignant, usually aggressive tumor composed of atypical, neoplastic melanocytes. "We identified LRIG2 expression in a human keratinocyte cell line (HaCaT), in an epidermal tumor cell line (A431), in a human melanoma cell line (A375), and in human tissue samples of cSCC patients and normal skin." (PMID 31580518, 2019). "Western blot analysis revealed that LRIG2 expression was significantly increased in human cSCC (A431) and melanoma (A375) cell lines compared to human keratinocytes (HaCaT)." (PMID 31580518, 2019). "Moreover, miR-149-5p inhibits melanoma cell proliferation by targeting LRIG2." (PMID 37259030, 2023).
oligodendroglioma (6 papers, 2013 to 2025). A well-differentiated (WHO grade II), diffusely infiltrating neuroglial tumor, typically located in the cerebral hemispheres. "The current investigation was prompted by our previous finding that LRIG2 expression is associated with poor oligodendroglioma patient survival." (PMID 24023893, 2013). "In addition, LRIG2 expression is associated with poor survival in oligodendroglioma and squamous cell carcinoma of the uterine cervix." (PMID 25353163, 2014). "In oligodendroglioma, LRIG2 expression is associated with poor survival, suggesting that LRIG2 might have different functions compared with LRIG1." (PMID 25353163, 2014). "In addition, LRIG2 expression is an independent prognostic factor associated with poor survival in oligodendroglioma and squamous cell carcinoma of the uterine cervix." (PMID 24023893, 2013). "By contrast, in oligodendroglioma and uterine cervical carcinoma patients, LRIG2 expression in the cytoplasm has been demonstrated to correlate with poor survival." (PMID 25013483, 2014). "Taken together, these two observations suggest that LRIG2 is an important regulator of oligodendroglioma initiation or progression." (PMID 24023893, 2013). "In this regard, it is noteworthy that the survival benefit of low LRIG2 expression in human oligodendroglioma patients was due to LRIG2 expression in the cancer cells only." (PMID 24023893, 2013). "In oligodendrogliomas LRIG2 expression correlates with a poor prognosis." (PMID 41201961, 2025).
cervical squamous cell carcinoma (4 papers, 2013 to 2022). A squamous cell carcinoma arising from the cervical epithelium. "In 129 cases of cervical squamous cell carcinoma, LRIG2 expression was a predictor of poor prognosis in early-stage disease." (PMID 28841699, 2017).